IRF8 (interferon regulatory factor 8)
Diseases named in the same sentence as IRF8 in open-access papers (continued):
Sharing a sentence is not in itself a finding about the gene and the disease.
leukemia (continued). "In addition to its leukemia suppressor role, IRF8 plays an important regulatory role in innate immune response." (PMID 29593731, 2018). "Therefore, gene regulation of Fanconi DNA repair proteins by IRF8 presents an important link between innate immune response and the leukemia suppressor role of IRF8." (PMID 29593731, 2018). "Several studies have shown a negative correlation between IRF8 and β-catenin signaling in myeloid cells and leukemia, indicating that IRF8 may at least partly suppress β-catenin signaling in solid tumors." (PMID 28388578, 2017). "Several possibilities may explain the contrasting role of IRF8 in miscellaneous leukemias." (PMID 33673123, 2021). "Furthermore, a 3-day administration of Dox did not influence the proliferation curves of APL cells in Neo-3G mice but did inhibit the proliferation of APL cells in Irf8-3G mice, which was accompanied by a reduction of leukemia burden, a promoted differentiation to c-Kit+CD11b++ mature APL cells." (PMID 28492552, 2017). "STAT1 binds to the IRF promoter region in colon cancer cells, while MBD1 inhibits IRF8 expression, which is another indication evidence that WT1 in leukemia and IRF8 are anticorrelated." (PMID 37250717, 2023). "Further studies will be needed to elucidate the mechanistic basis of the IRF8/MEF2D module activation and the selective, context-specific dependence on these TFs for the expression of common oncogenes in KMT2Ar leukemia." (PMID 35301220, 2022). "Because IRF8 and MEF2D were the most strongly selective transcriptional dependencies of KMT2Ar leukemia and most strongly overexpressed core TFs in primary KMT2Ar AML samples, we focused attention on these two TFs." (PMID 35301220, 2022). "Evidence has suggested that IRF8 acts as a TSG in multiple cancers, including leukemia, renal cancer, and soft tissue sarcoma, via regulating cell proliferation, apoptosis, cell cycle distribution, cell invasion, and metastasis." (PMID 28388578, 2017). "This gene set, which includes several critical regulators of myelopoiesis and leukemia including BCL2, C-MYC and IRF8, was also downregulated in other AML cell lines sensitive to I-BET." (PMID 24220271, 2014). "Relatively decreased expression in the bone marrow of subjects with chronic myeloid leukemia (CML) compared with nonleukemic subjects suggests that Irf8 functions as a leukemia suppressor." (PMID 37247756, 2023). "This concept is further illustrated by the KMT2A-like leukemias, which express high levels of IRF8 and MEF2D despite the absence of a KMT2A translocation." (PMID 35301220, 2022). "While our data do not reveal a fusion protein-driven mechanism of IRF8/MEF2D axis activation in KMT2A-rearranged leukemia, we found that it correlates with the degree of myeloid differentiation." (PMID 35301220, 2022). "Consistently, in the CRISPR screen only the AML cells, but not other leukemia cells, showed strongly reduced proliferation upon IRF8 deletion." (PMID 33673123, 2021). "Oncogenes (YAP1, Survivin) were shown to be repressed and TSGs (p21, PTEN, CASP1) upregulated under IRF8 overexpression in renal cancer, and negative feedback occurred between IRF8 and β-catenin in leukemia." (PMID 28388578, 2017). "Although IRF-8 was originally discovered as an IFN-γ inducible transcription factor essential for normal myelopoiesis and as a tumor suppressor of certain leukemias, our findings revealed a new functional role for IRF-8 in non-hematopoietic malignancies." (PMID 23028998, 2012). "Indeed, several of the IRF8/MEF2D direct target genes, such as MYC, HOXA9, and ZEB2, are highly expressed and essential in non-KMT2Ar leukemias and normal hematopoietic progenitors that do not express high levels of IRF8/MEF2D." (PMID 35301220, 2022).
leukemia (continued). "Among the TFs that we and others identified to be selectively essential and overexpressed in KMT2A-rearranged leukemia, MEF2C, RUNX2, and MEIS1 are well-established direct targets of KMT2A fusion oncoproteins, prompting us to consider that one of these TFs drives IRF8 overexpression." (PMID 35301220, 2022). "Nonetheless, our bioinformatical and cellular investigations strongly support a pro-tumorigenic role of IRF8 in a subset of AML cells, but not in other leukemia cells." (PMID 33673123, 2021). "Therefore, more work is required to better understand the opposing role of IRF8 in AML and non-AML leukemia cells." (PMID 33673123, 2021). "For example, IRF8 may interact with distinct cofactors in AML and non-AML leukemia, which may alter its transcriptional activity, and consequently its impact on transcription." (PMID 33673123, 2021). "Unlike IRF8, which plays an essential role in myeloid development, MEF2D has no assigned role in normal hematopoiesis, prompting us to hypothesize that it represents a leukemia-specific transcriptional addiction." (PMID 35301220, 2022).
viral infections (23 papers, 2009 to 2025). "We sought to describe the effect on hematopoiesis and immunity of the compound heterozygous R83C/R291Q mutation of IRF8, which is present in a patient with recurrent viral infection, granuloproliferation, and intracerebral calcification." (PMID 29128673, 2018). "The bi-allelic K108E mutation of IRF8 caused an AR severe immunodeficiency in which there was a complete absence of circulating monocytes and DCs from peripheral blood, which resulted in disseminated BCGosis, oral candidiasis, and viral infections." (PMID 36569938, 2022). "are associated with anti-viral infection, such as IRF8 (3 h.p.i)." (PMID 36209057, 2022). "Irf8 knockout mice show increased viral infections, reduced IL-12p40 and IFN-gamma production, neutrophil expansion and a blast crisis phenotype, and lower numbers of pDCs and CD8α+ mDCs, but not CD11b+DCs." (PMID 41229418, 2025). "Taken together, IRF8 deletion during PEDV infection further enhances the viral infection process and produces a severe inflammatory response in the host." (PMID 37593742, 2023). "Decreased expression levels of key apoptotic proteins further illustrate that high expression of IRF8 is beneficial for viral infection-activated apoptosis and changes in biological processes, such as the cell cycle." (PMID 37593742, 2023). "Despite that IRF8 is found to be partially localized in cytoplasm, the nuclear-localized IRF8 works with IRF3 to enable rapid IFN gene transcription in human blood monocytes following viral infection." (PMID 35464458, 2022). "Among them, IRF8 controls the expression of IFNα- and IFNβ-regulated genes that are induced by viral infection." (PMID 36209057, 2022). "A unique role of Irf8 in monocytes also provides an explanation on the notion that these cells express higher levels of antiviral genes following viral infection than other cells." (PMID 35973990, 2022). "We checked JEV viral load and NS1 protein expression in WT and Irf8−/− infected mice to confirm that the mice died due to viral infection." (PMID 34379515, 2021). "In the absence of any evidence of direct interaction between rCsBPI and the virus, it is likely that the inhibitory effect of rCsBPI on viral infection is the result of rCsBPI-induced expression of the genes, such as IRF8, involved in antiviral immunity." (PMID 27105425, 2016). "Subsequent autosomal recessive IRF8 deficiency cases were also reported to have recurring viral infections, BCG susceptibility, absent or decreased monocyte and DC populations, and decreased IL-12 and IFN-γ production." (PMID 41229418, 2025). "Viral infection in mice induces IRF8 expression in infected brains." (PMID 34379515, 2021). "Mutations affecting IRF family members IRF1, IRF3, IRF7, IRF8, or IRF9 have been described in patients presenting with inborn errors of immunity (IEI) highlighting the importance of these factors for the cellular host defense against mycobacterial and/or viral infections." (PMID 37809068, 2023). "We also observed elevated transcript levels for several restriction factor-encoding genes (IFIT and IFITMs) and pro-inflammatory factors (STAT1, IRF8) known to be activated in response to viral infections, including HIV-143–45, which may contribute to the EC phenotype." (PMID 38168352, 2023). "We next examined whether IRF8 plays a role in T cell-mediated regulation of viral infection." (PMID 27171004, 2016). "However, P2’s early life history of repeated viral infections, failure to thrive, and poorly formed granulomatous changes on duodenal biopsy are notable, and do raise the question of an underlying IEI, perhaps related to their IRF8 variant causing an as of yet undefined immune impact." (PMID 41229418, 2025). "This protein is activated by TLRs during the immune response and regulates gene expression in response to cytokines, stress, and bacterial or viral infections, as well as notably the IFN regulatory factors (IRFs, particularly IRF3, IRF4, and IRF8)." (PMID 40665467, 2025).
viral infections (continued). "IRF8 also regulates expression of genes stimulated by IFN-alpha and IFN-beta that are typically induced during viral infection, and the latter is significantly upregulated in fetal thymus and spleen following PRRSV infection." (PMID 36845393, 2023). "However, pDCs express significantly less Irf8, which is involved mainly in the production of type I IFN after viral infections." (PMID 34361114, 2021). "Here we found that IRF8 showed a relatively higher frequency of putative TFBSs in the promoters of genes in the cluster 3, which includes the aconitate decarboxylase 1 (ACOD1) gene whose expression can be induced by bacterial or viral infections." (PMID 31382472, 2019). "However, other individual IRF family members (e.g., IRF-1 or IRF-8), which are known to induce the IFN-β response after viral infection or engagement of PRR in some systems, did not have a dominant regulatory effect in the context of WNV infection." (PMID 19798431, 2009).
melanoma (19 papers, 2013 to 2025). A malignant, usually aggressive tumor composed of atypical, neoplastic melanocytes. "In conclusion, this study significantly enhances our understanding of the molecular mechanisms underlying BRAF-driven melanoma progression by elucidating the TRIM63/IRF-8 axis." (PMID 41315179, 2025). "Decreased IRF8 expression in CD8+ T cells has been associated with an increase in melanoma growth while an increase in IRF8 has been reported in DLBCL tumor tissues." (PMID 36078039, 2022). "Conversely, IRF-8 deficient splenocytes displayed poor migratory extent toward the tumor, which reflected a high invasion ability of melanoma cells." (PMID 33842539, 2021). "The two side chambers were loaded with spleen cells (from immunocompetent or IRF-8 deficient mice) and B16.F10 melanoma cells." (PMID 33842539, 2021). "IRF8 deficiency in macrophages significantly increased metastasis and expression of metastatic-associated genes in the mouse models of mammary cancer and melanoma, and correlated with reduced survival in human breast and lung cancers and melanoma." (PMID 32486098, 2020). "We observed that IRF8 deficiency in CD4+ T cells favoured melanoma growth in both lung metastasis and subcutaneous tumour models." (PMID 29233972, 2017). "The goal of the study was to investigate the role of IRF-8 immune deficiency on immune response to melanoma." (PMID 23616948, 2013). "In conclusion, these results suggested that the regulatory axis of TRIM63 pS69/IRF-8 plays a critical role in clinical outcomes of human melanoma." (PMID 41315179, 2025). "Wild-type IRF-8 and the K250R mutant, a ubiquitination-defective variant, were overexpressed in BRAF-mutant melanoma cell lines." (PMID 41315179, 2025). "To investigate the mechanism, we primarily detect that protein stability of IRF-8 in BRAF V600E melanoma cells, indicating that cycloheximide treatment significantly decreased IRF-8 protein levels, partially restored by TRIM63 deletion." (PMID 41315179, 2025). "Herein, we identify that TRIM63-mediated degradation of IRF-8 provides a mechanistic explanation for observed immune evasion in numerous melanoma cases." (PMID 41315179, 2025). "In the B16F10 melanoma mouse model, IRF8 was shown to be downregulated in bone-marrow-derived myeloid cells in an ID1-dependent fashion by tumor-derived soluble factors, most notably TGF-β." (PMID 31953577, 2020). "This was done by introducing fluorescently labeled melanoma cells and splenocytes from either WT or IRF8 knockout mice into different chambers of the device that were connected by microfluidics channels and performing live cell tracking of the cells." (PMID 29883385, 2018). "Taken together, these results suggest that IRF-8 regulates melanoma progression and invasiveness by soluble factors released by immune cells in the TME." (PMID 29438283, 2018). "To determine the effects of IRF8 in Th9 cell development during melanoma growth, we used the B16F10 model and studied tumour growth in WT, Irf8f/fCd4cre and Irf8+/+Cd4cre mice." (PMID 29233972, 2017). "The results evidenced a marked inability of IRF-8−/− immune cells to migrate toward and interact with melanoma cells with respect to WT cells." (PMID 23616948, 2013). "Notably, the overexpression of the K250R mutant of IRF-8 exhibited a more pronounced inhibitory effect on melanoma cell proliferation compared to the wild-type protein." (PMID 41315179, 2025). "IRF-8 has been identified as a potential tumor suppressor in the progression of melanoma." (PMID 41315179, 2025). "B16 melanoma cells, immune cells isolated from spleen of wild-type (WT) and IRF-8 KO mice." (PMID 39459070, 2024). "Furthermore, Irf8+32−/− mice vaccinated with opt-TRP-1 were protected from lung metastasis of B16F10 melanoma cells to a similar degree as C57BL/6 mice." (PMID 39559560, 2024).
melanoma (continued). "In this study, we observed that IRF8 expression level is significantly higher in tumor cells at the single cell level in responders than in non-responders in response to nivolumab immunotherapy in human melanoma patients." (PMID 36672246, 2023). "Poor tumoral homing of DCs and T cells was observed in melanoma-bearing IRF8 KO mice." (PMID 36078039, 2022). "Interestingly, we observed significant downregulation of the IRF transcription factor family members (IRF1, IRF2, IRF5, IRF8) corresponding to attenuated interferon signaling in TRIM28HIGH melanomas, probably as a consequence of low immune cell infiltration." (PMID 33076560, 2020). "In vivo, IRF8 is essential for the anti-tumour effects of Th9 cells in mouse melanoma models." (PMID 29233972, 2017). "Thus, splenic immune cells from IRF-8−/− mice or WT controls were allowed to interact with B16.F10 melanoma cells into the microfluidic structure." (PMID 23616948, 2013). "Likewise, marked tumor infiltration and systemic expansion of CD11b+Gr-1+MDSC was found to be associated with enhanced tumor growth and malignant phenotype in an immunocompromised IRF-8−/− mouse model transplanted with B16.F10 melanoma." (PMID 23616948, 2013). "Subsequently, to investigate the impact of TRIM63 on IRF-8, we conducted TRIM63 depletion, which resulted in an increase in IRF-8 protein levels specifically in melanoma cells harboring BRAF V600E mutation, while no such effect was observed in cells with wild-type BRAF." (PMID 41315179, 2025). "We showed that IRF8 is decreased in HLA-DRlow monocytic MDSC compared to HLA-DRhigh monocytes in the blood of stage III and IV melanoma patients." (PMID 31953577, 2020). "The results of correlation analysis showed a significant, positive correlation (cor > 0.6, p-value < 0.05) between the expression of four hub genes (IRF1, CD8A, IRF8, and SELL) and three biomarkers in melanoma." (PMID 32316408, 2020). "In conclusion, six hub genes (IRF1, JAK2, CD8A, IRF8, STAT5B, and SELL) were discovered to distinguish the response of melanoma patients under anti-PD-1 immunotherapy via WGCNA and integrated bioinformatics." (PMID 32316408, 2020). "When both IRF8 and TRIM63 were simultaneously knocked down, the cell proliferation abilities were partially restored, suggesting that the TRIM63/IRF8 axis plays a critical role in promoting melanoma cell proliferation." (PMID 41315179, 2025). "Taken together, IRF1, JAK2, CD8A, IRF8, STAT5B, and SELL may serve as predictive therapeutic biomarkers for melanoma and could facilitate future anti-PD-1 therapy." (PMID 32316408, 2020). "Further, the signal was robustly detected in melanoma samples and exhibited a positive correlation with phosphorylation levels of ERK1/2, while displaying a negative correlation with IRF-8." (PMID 41315179, 2025). "CYT-high primary melanomas on the other hand, did not have recurrent copy number amplifications above the threshold (Q value = 0.25), but rather had loses at 9p21.3 (CDKN2A/B), 9q34.11 (CDK9) and 16q24.2 (IRF8)." (PMID 33779796, 2021). "Finally, the results suggested that the expression of six genes including IRF1, JAK2, CD8A, IRF8, STAT5B, and SELL had a significant ability to distinguish the responders from non-responders to anti-PD-1 therapy in melanoma with AUC > 0.6 and pAUC > 0.7." (PMID 32316408, 2020).